FAM174C (family with sequence similarity 174 member C)
Synonyms: FLJ20640; formerly C19orf24
Tractability: Antibody: its Gene Ontology location is reachable by antibodies, with high confidence; UniProt predicts a signal peptide or a membrane-spanning region.
Gene: Protein-coding gene on chromosome 19 (1,276,021 to 1,279,244, forward strand). Ensembl gene ENSG00000228300.
Subcellular location: Membrane
Subcellular location (Human Protein Atlas): Nuclear speckles; Golgi apparatus
Genetic constraint (gnomAD): Loss-of-function variants: 13 observed, 7.52 expected, observed/expected ratio (o/e) 1.73, 90% interval 1.05 to 1.96. That is too few expected variants to judge how well the gene tolerates losing a copy. Missense variants: 194 observed, 115.04 expected, observed/expected ratio (o/e) 1.69, 90% interval 1.5 to 1.89. Synonymous variants: 126 observed, 68.68 expected, observed/expected ratio (o/e) 1.83, 90% interval 1.57 to 1.97.